TMEM35A (transmembrane protein 35A)
Description:
Molecular chaperone which mediates the proper assembly and functional expression of the nicotinic acetylcholine receptors (nAChRs) throughout the brain. Essential for the proper folding, assembly, function and surface trafficking of alpha-7 (CHRNA7), alpha-4-beta-2, alpha-3-beta-2 and alpha-3-beta-4 receptors. Stably associates with ribophorin-1 (RPN1) and ribophorin-2 (RPN2) (components of the oligosaccharyl transferase (OST) complex) and with calnexin (CANX), both of which are critical for NACHO-mediated effects on CHRNA7 assembly and function (By similarity). Facilitates the proper folding and assembly of alpha-6-beta-2 and alpha-6-beta-2-beta-3 receptors and acts at early stages of the nAChRs subunit assembly. Promotes the expression of the alpha-4(2):beta-2(3) stoichiometric form over the alpha-4(3):beta-2(2) form.
Synonyms: NACHO; TMEM35; FLJ14084; TUF-1
Tractability: Small molecule: a structure with a bound ligand is known. Antibody: UniProt predicts a signal peptide or a membrane-spanning region.
Gene: Protein-coding gene on chromosome X (101,078,879 to 101,096,367, forward strand). Ensembl gene ENSG00000126950.
Subcellular location: Peroxisome membrane; Cytoplasmic vesicle; Endoplasmic reticulum membrane
Subcellular location (Human Protein Atlas): Vesicles; Cytosol; Focal adhesion sites
Gene Ontology:
Molecular function: acetylcholine receptor regulator activity; protein binding
Biological process: chaperone-mediated protein complex assembly; positive regulation of protein localization to cell surface
Cellular component: endoplasmic reticulum; cytoplasmic vesicle; endoplasmic reticulum membrane; peroxisomal membrane
Homologues: Orthologues: chimpanzee TMEM35A (100% identical), macaque TMEM35A (100% identical), rabbit TMEM35A (99% identical), guinea pig TMEM35A (99% identical), rat Tmem35a (98% identical), dog TMEM35A (97% identical), mouse Tmem35a (97% identical), pig TMEM35A (95% identical), zebrafish tmem35 (78% identical), tropical clawed frog tmem35a (77% identical), Drosophila melanogaster CG13920 (34% identical). Paralogues in human: TMEM35B (22% identical).
Diseases named in the same sentence as TMEM35A in open-access papers:
TMEM35A is named in the same sentence as 7 diseases in open-access papers, as found by Europe PMC text mining. Sharing a sentence is not in itself a finding about the gene and the disease. The quoted sentences say what the papers report.
tumor (1 paper, 2025). "Genes with reported anti-tumor functions, including SCGB1D2 (Secretoglobin Family 1D Member 2, lipophilin B), FKBP5, CD52, DLK1, GALNT9, GNG2, GDNF, and TMEM35A, were significantly upregulated after CUDC-907 + MPA treatment and validated by RT-PCR." (PMID 41262902, 2025).
TMEM35A also shares sentences with these, for which no sentence is quoted: neuroblastoma (2 papers); cancer (1); gastritis (1); hyperlipidemia (1); infection (1); Obesity (1).